CIPC (CLOCK interacting pacemaker)
Description:
Transcriptional repressor which may act as a negative-feedback regulator of CLOCK-BMAL1 transcriptional activity in the circadian-clock mechanism. May stimulate BMAL1-dependent phosphorylation of CLOCK. However, the physiological relevance of these observations is unsure, since experiments in an animal model showed that CIPC is not critially required for basic circadian clock.
Synonyms: KIAA1737
Tractability: PROTAC: ubiquitination databases record sites on it.
Gene: Protein-coding gene on chromosome 14 (77,098,126 to 77,117,287, forward strand). Ensembl gene ENSG00000198894.
Subcellular location: Nucleus; Cytoplasm, cytosol
Subcellular location (Human Protein Atlas): Cytosol; Nucleoplasm; Nucleoli
Pathways (Reactome):
Circadian clock: Phosphorylated BMAL1:CLOCK (ARNTL:CLOCK) activates expression of core clock genes
Gene Ontology:
Molecular function: protein binding
Biological process: negative regulation of circadian rhythm; negative regulation of DNA-templated transcription
Cellular component: cytosol; nucleoplasm; nucleus
Genetic constraint (gnomAD): Loss-of-function variants: 12 observed, 30.39 expected, observed/expected ratio (o/e) 0.39, 90% interval 0.25 to 0.64. The upper end of that interval is the gene's LOEUF score, 0.64, which puts it in group 2 of 6, group 1 being the genes least tolerant of losing a copy. Missense variants: 417 observed, 512.52 expected, observed/expected ratio (o/e) 0.81, 90% interval 0.75 to 0.88. Synonymous variants: 170 observed, 199.82 expected, observed/expected ratio (o/e) 0.85, 90% interval 0.75 to 0.97.
Homologues: Orthologues: chimpanzee CIPC (99% identical), macaque CIPC (99% identical), dog CIPC (94% identical), guinea pig CIPC (89% identical), rat Cipc (87% identical), mouse Cipc (86% identical), rabbit CIPC (84% identical), pig CIPC (82% identical), tropical clawed frog cipc (29% identical), zebrafish cipcb (23% identical), zebrafish cipca (23% identical).
Diseases named in the same sentence as CIPC in open-access papers:
CIPC is named in the same sentence as 7 diseases in open-access papers, as found by Europe PMC text mining. Sharing a sentence is not in itself a finding about the gene and the disease. The quoted sentences say what the papers report.
acute myeloid leukemia (1 paper, 2025). Acute myeloid leukemia (AML) is a group of neoplasms arising from precursor cells committed to the myeloid cell-line differentiation. "Public datasets and bioinformatics tools were used to examine CIPC gene expression in healthy patients and acute myeloid leukemia (AML) samples." (PMID 40700255, 2025).
leukemia (1 paper, 2025). A malignant (clonal) hematologic disorder, involving hematopoietic stem cells and characterized by the presence of primitive or atypical myeloid or lymphoid cells in the bone marrow and the blood. "This work reviews the relatively little-known negative regulator of the circadian cycle, CIPC, emphasizing its significant role in cancer, particularly leukemia." (PMID 40700255, 2025). "Altered CIPC expression may contribute to leukemogenesis by inhibiting circadian genes, which are often disrupted in leukemia." (PMID 40700255, 2025). "CIPC (CLOCK-interacting pacemaker) has been studied as a negative regulator of the CLOCK–BMAL1 complex, focusing on its role in cancer, particularly leukemias." (PMID 40700255, 2025).
tumor (3 papers, 2016 to 2025). "An image was generated containing expression comparisons across 34 tumor types available in the tool, along with a boxplot specifically depicting CIPC expression in AML." (PMID 40700255, 2025).
cancer (2 papers, 2020 to 2025). A tumor composed of atypical neoplastic, often pleomorphic cells that invade other tissues. "Subsequently, the DAVID database was used to perform functional annotation using KEGG, REACTOME, and WIKIPATHWAYS, aiming to identify which pathways CIPC may influence and to highlight those already known to be associated with cancer." (PMID 40700255, 2025). "Although these findings underscore the relevance of CIPC in AML, further studies are necessary to validate these results and elucidate the precise mechanistic role of CIPC in cancer." (PMID 40700255, 2025). "Additional studies are needed to validate these findings and explore the detailed role of CIPC in cancer development." (PMID 40700255, 2025). "Although a direct role for CIPC in human disease has not been established, its influence on cell proliferation and Erk signaling suggests potential relevance to disorders involving abnormal cell growth, such as cancer." (PMID 40700255, 2025).
CIPC also shares sentences with these, for which no sentence is quoted: acute kidney injury (1 paper); melanoma (1); Sepsis (1).